COX6B2 (cytochrome c oxidase subunit 6B2)
Description:
Component of the cytochrome c oxidase, the last enzyme in the mitochondrial electron transport chain which drives oxidative phosphorylation. The respiratory chain contains 3 multisubunit complexes succinate dehydrogenase (complex II, CII), ubiquinol-cytochrome c oxidoreductase (cytochrome b-c1 complex, complex III, CIII) and cytochrome c oxidase (complex IV, CIV), that cooperate to transfer electrons derived from NADH and succinate to molecular oxygen, creating an electrochemical gradient over the inner membrane that drives transmembrane transport and the ATP synthase. Cytochrome c oxidase is the component of the respiratory chain that catalyzes the reduction of oxygen to water. Electrons originating from reduced cytochrome c in the intermembrane space (IMS) are transferred via the dinuclear copper A center (CU(A)) of subunit 2 and heme A of subunit 1 to the active site in subunit 1, a binuclear center (BNC) formed by heme A3 and copper B (CU(B)). The BNC reduces molecular oxygen to 2 water molecules using 4 electrons from cytochrome c in the IMS and 4 protons from the mitochondrial matrix.
Synonyms: CT59; COXVIB2; FLJ32865
Tractability: Antibody: UniProt places it where antibodies can reach, with medium confidence; the Human Protein Atlas places it where antibodies can reach.
Gene: Protein-coding gene on chromosome 19 (55,349,306 to 55,354,719, reverse strand). Ensembl gene ENSG00000160471.
Subcellular location: Mitochondrion inner membrane
Subcellular location (Human Protein Atlas): Cytosol; Nucleoplasm; Plasma membrane
Pathways (Reactome):
Metabolism: Complex IV assembly; Respiratory electron transport
Cellular responses to stimuli: Cytoprotection by HMOX1
Gene Ontology:
Molecular function: protein binding
Biological process: oxidative phosphorylation
Cellular component: mitochondrial crista; mitochondrion; mitochondrial inner membrane; respiratory chain complex IV
Genetic constraint (gnomAD): Loss-of-function variants: 12 observed, 11.96 expected, observed/expected ratio (o/e) 1, 90% interval 0.64 to 1.61. The upper end of that interval is the gene's LOEUF score, 1.61, which puts it in group 6 of 6, group 1 being the genes least tolerant of losing a copy. Missense variants: 130 observed, 113.7 expected, observed/expected ratio (o/e) 1.14, 90% interval 0.99 to 1.32. Synonymous variants: 56 observed, 41.27 expected, observed/expected ratio (o/e) 1.36, 90% interval 1.09 to 1.69.
Homologues: Orthologues: chimpanzee COX6B2 (99% identical), macaque COX6B2 (80% identical), mouse Cox6b2 (80% identical), dog COX6B2 (78% identical), pig COX6B2 (74% identical), rat Cox6b2 (64% identical), guinea pig COX6B2 (60% identical), zebrafish cox6b2 (56% identical), zebrafish cox6b1 (51% identical), tropical clawed frog cox6b1 (48% identical), Drosophila melanogaster COX6B (45% identical), Caenorhabditis elegans cox-6B (32% identical). Paralogues in human: COX6B1 (52% identical).
Diseases named in the same sentence as COX6B2 in open-access papers:
COX6B2 is named in the same sentence as 17 diseases in open-access papers, as found by Europe PMC text mining. Sharing a sentence is not in itself a finding about the gene and the disease. The quoted sentences say what the papers report.
lung adenocarcinoma (5 papers, 2020 to 2024). A carcinoma that arises from the lung and is characterized by the presence of malignant glandular epithelial cells. "The role of 9 OXPHOS related genes in cancer were reported, such as COX6B2 promoted oxidative phosphorylation, proliferation, and survival in human lung adenocarcinoma." (PMID 38698303, 2024). "More recently, it was demonstrated that human lung adenocarcinoma cells co-opt the expression of the normally sperm-specific CcO subunit COX6B2 to promote CcO incorporation into SCs and increase OXPHOS efficiency." (PMID 35478774, 2022). "COX6B2 is expressed in human lung adenocarcinoma (LUAD) and expression correlates with reduced survival time." (PMID 32990599, 2020). "Indeed, and consistently with previous reports on CT genes, the expression of the meiosis specific gene HORMAD1, the MAGE-A gene family, and the sperm specific cytochrome c oxidase COX6B2, we found that a high GC signature score correlates with poor prognosis in lung adenocarcinoma." (PMID 33348709, 2020).
lung carcinoma (4 papers, 2020 to 2025). "Cytochrome c oxidase subunit 6B2 (COX6B2) is highly expressed in human lung cancer and is correlated with a reduced survival time in cancer patients." (PMID 35574342, 2022). "(D) COX6B2 mRNA expression (RNA-seq RSEM, log2(norm count +1)) from TCGA Lung Cancer dataset." (PMID 32990599, 2020).
breast carcinoma (2 papers, 2011 to 2020). "Our initial gene expression comparisons identified COX6B2 as being down regulated in rho0 and breast cancer cells." (PMID 21935467, 2011). "ChIP data from human breast cancer cells indicates that HIF-1 is bound near the COX6B2 promoter." (PMID 32990599, 2020).
glaucoma (1 paper, 2022). Increased pressure in the eyeball due to obstruction of the outflow of aqueous humor. "Supporting this view is our previous observation that peptain-1 restores retinal mitochondrial cytochrome c oxidase subunit 6b2 levels in a rodent model of glaucoma." (PMID 36379926, 2022).
non-small cell lung carcinoma (1 paper, 2020). A group of at least three distinct histological types of lung cancer, including non-small cell squamous cell carcinoma, adenocarcinoma, and large cell carcinoma. "In a large-scale lossof-function analysis to annotate the contribution of individual CTAs to neoplastic behaviors, we found that COX6B2 is essential for survival of non-small cell lung cancer (NSCLC) cell lines." (PMID 32990599, 2020).
cancer (7 papers, 2018 to 2024). A tumor composed of atypical neoplastic, often pleomorphic cells that invade other tissues. "We did observe a moderate correlation with the complex IV subunit, COXIV, suggesting COX6B2 accumulation coincides with increased mitochondria in cancer cells." (PMID 32990599, 2020). "Together it is conceivable that the loss of COX6B2 in PARL-deficient mice might be the cause of the decrease in complex IV proteins and complex IV activity, similar to what was described before in cancer cells." (PMID 38182793, 2024). "Moreover, we found that the mRNA level of COX6B2 in PDAC tissues was top ranked among all 30 studied cancer types in the database of TCGA." (PMID 32415061, 2020). "Consequently, COX6B2-expressing cancer cells display a proliferative advantage, particularly in low oxygen." (PMID 32990599, 2020). "We propose that enhanced accumulation of COX6B2 is an acquired trait that is essential for OXPHOS in LUAD and perhaps additional cancers." (PMID 32990599, 2020). "Collectively, these results further demonstrated that the high levels of COX6B2 in PDAC were more likely to promote the metastatic ability of PDAC cells and had little effect on cancer cell growth and tumor formation." (PMID 32415061, 2020). "Administration of metformin was revealed to be able to inactivate the COX6B2 mediated OXPHOS/ATP/purinergic receptor pathway and inhibit cancer cell metastasis." (PMID 32415061, 2020). "Although, COX6B2 KD in all three studied cancer cell lines inhibited the migration of PDAC cells in the performed wound healing assays, re-expression of COX6B2 in COX6B2 KD 8988 cells restored their migration ability." (PMID 32415061, 2020). "Altogether, these results indicated that COX6B2 can modify the metastatic potential of PDAC cells without affecting cancer cell growth and tumor formation." (PMID 32415061, 2020). "Here, we report that COX6B2 drive metastasis but not cancer cell proliferation in PDAC by enhancing oxidative phosphorylation function (OXPHOS)." (PMID 32415061, 2020). "The effect of COX6B2 on the metastatic potential of PDAC cells was much more significant when using the transwell assay, a commonly used assay to test the migratory ability of cancer cells." (PMID 32415061, 2020). "We found that suppression of COX6B2 did not affect cancer cell growth in all three studied cancer cell lines." (PMID 32415061, 2020).
tumor (7 papers, 2020 to 2025). "COX6B2 encodes cytochrome c oxidase subunit 6B2, which is involved in the metabolic reprogramming of several tumor cells by enhancing oxidative phosphorylation." (PMID 37446030, 2023). "One of the most surprising aspects of our study was the loss of tumor cell viability following the depletion of COX6B2." (PMID 32990599, 2020). "Through this screen and subsequent validation, NY-ESO-1, FTHL17, and SPATA19 were identified as required for tumor cell proliferation and COX6B2 and CALR3 as essential for survival." (PMID 34830845, 2021). "Collectively, these findings indicate that COX6B2 is essential for respiration and mitochondrial integrity in tumor cells." (PMID 32990599, 2020). "Here, we report that COX6B2 enhances mitochondrial oxidative phosphorylation (OXPHOS) in tumor cells." (PMID 32990599, 2020). "Complementing the gain-of-function phenotype observed, we found that depletion of COX6B2 severely reduces tumor growth and final tumor mass." (PMID 32990599, 2020). "We propose that tumor cells that express and engage the COX6B2-based, sperm-specific mechanism can overcome this innate barrier to transformation that would otherwise restrict cell survival." (PMID 32990599, 2020). "Moreover, depleting SDCBP leads to upregulation of BACH1-repressed electron transport chain (ETC) genes, such as NDUFA4 and COX6B2, and increases mitochondrial activity, enhancing anti-tumor efficacy of metformin against TNBC both in vitro and in vivo." (PMID 40263598, 2025). "Based on the observed decrease in OCR, we asked whether tumor cell viability was diminished following COX6B2 depletion in LUAD cells." (PMID 32990599, 2020). "COX6B2 is both necessary and sufficient for growth of human tumor xenografts in mice." (PMID 32990599, 2020). "We next sought to determine whether COX6B2 was necessary and/or sufficient for tumor growth in vivo." (PMID 32990599, 2020). "Thus, COX6B2 is essential for survival of LUAD tumor cells as its suppression reduces ATP, compromises mitochondrial integrity thereby generating excess ROS that leads to apoptosis or senescence." (PMID 32990599, 2020). "In turn, COX6B2 becomes a liability that may be exploited for tumor selective targeting of OXPHOS." (PMID 32990599, 2020). "Convincible, knockdown of COX6B2 elicits cell apoptosis or senescence due to a decrease in OXPHOS and mitochondrial membrane collapse in tumour xenograft mice." (PMID 35574342, 2022). "COX6B2, a testis-specific subunit of cytochrome c oxidase (complex IV), enhances mitochondrial OXPHOS in tumor cells, which in turn promotes proliferation." (PMID 34830845, 2021). "Given the pro-proliferative phenotype following COX6B2 expression, we next examined the consequences of its depletion on OXPHOS and tumor cell viability." (PMID 32990599, 2020). "In contrast, silencing of COX6B2 attenuates OXPHOS, reduces tumor cell viability and dramatically decreases growth in vivo." (PMID 32990599, 2020). "Overexpression of COX6B2 enhances the activity of cytochrome c oxidase complex IV and increases oxidative phosphorylation (OXPHOS) and NAD+ generation, leading to an increase in ATP production and robust tumour cell proliferation." (PMID 35574342, 2022). "As COX6B2 enhances OXPHOS, its loss would be expected to reduce ATP levels and the NAD+/NADH ratio and slow proliferation, but not necessarily kill tumor cells." (PMID 32990599, 2020). "We found that COX6B2 protein expression is low or undetectable in normal lung tissue, but present in all tumor-derived tissues irrespective of stage and grade." (PMID 32990599, 2020). "Immunohistochemical staining revealed that treatment of the 4T1 tumor with adenoviral SDCBP shRNA significantly decreased the expression levels of SDCBP, BACH1, and Ki67, but increased the expression levels of NDUFA4 and COX6B2 compared with those in the control and metformin-treated groups." (PMID 40263598, 2025).
tumor (continued). "Furthermore, immunohistochemical staining of COX6B2 in a panel of human non-malignant (n = 22) and LUAD tissues (n = 32) indicated accumulation of COX6B2 in tumor, but not non-malignant tissues." (PMID 32990599, 2020).
COX6B2 also shares sentences with these, for which no sentence is quoted: arrhythmogenic right ventricular cardiomyopathy (1 paper); asthenozoospermia (1); cardiac hypertrophy (1); dilated cardiomyopathy (1); heart failure (1); hypertrophic cardiomyopathy (1); Infertility (1); laryngeal carcinoma (1); melanoma (1); Obesity (1).